CD209 (CD209 molecule)
Description:
Pathogen-recognition receptor expressed on the surface of immature dendritic cells (DCs) and involved in initiation of primary immune response. Thought to mediate the endocytosis of pathogens which are subsequently degraded in lysosomal compartments. The receptor returns to the cell membrane surface and the pathogen-derived antigens are presented to resting T-cells via MHC class II proteins to initiate the adaptive immune response. On dendritic cells (DCs) it is a high affinity receptor for ICAM2 and ICAM3 by binding to mannose-like carbohydrates. May act as a DC rolling receptor that mediates transendothelial migration of DC presursors from blood to tissues by binding endothelial ICAM2. Forms a first contact between DC and resting T cell, througth ICAM3 binding, facilitating the downstream DC-T cell clustering process and DC-induced proliferation of resting T Cells. (Microbial infection) Acts as an attachment receptor for HIV-1 and HIV-2. (Microbial infection) Acts as an attachment receptor for Ebolavirus. (Microbial infection) Acts as an attachment receptor for Cytomegalovirus. (Microbial infection) Acts as an attachment receptor for HCV. (Microbial infection) Acts as an attachment receptor for Dengue virus. (Microbial infection) Acts as an attachment receptor for Measles virus. (Microbial infection) Acts as an attachment receptor for Herpes simplex virus 1. (Microbial infection) Acts as an attachment receptor for Influenzavirus A. (Microbial infection) Acts as an attachment receptor for SARS-CoV. (Microbial infection) Acts as an attachment receptor for Japanese encephalitis virus. (Microbial infection) Acts as an attachment receptor for Lassa virus. Acts as an attachment receptor for Marburg virusn. (Microbial infection) Acts as an attachment receptor for Respiratory syncytial virus. (Microbial infection) Acts as an attachment receptor for Rift valley fever virus and uukuniemi virus. (Microbial infection) Acts as an attachment receptor for West-nile virus. (Microbial infection) Probably recognizes in a calcium-dependent manner high mannose N-linked oligosaccharides in a variety of bacterial pathogen antigens, including Leishmania pifanoi LPG, Lewis-x antigen in Helicobacter pylori LPS, mannose in Klebsiella pneumonae LPS, di-mannose and tri-mannose in Mycobacterium tuberculosis ManLAM and Lewis-x antigen in Schistosoma mansoni SEA. Recognition of M.tuberculosis by dendritic cells occurs partially via this molecule.
Synonyms: DC-SIGN; DC-SIGN1; CLEC4L; hDC-SIGN; CDSIGN
Tractability: Small molecule: a structure with a bound ligand is known. Antibody: UniProt places it where antibodies can reach, with high confidence; its Gene Ontology location is reachable by antibodies, with high confidence; UniProt predicts a signal peptide or a membrane-spanning region. PROTAC: a small molecule that binds it is known.
Target class: Surface antigen
Gene: Protein-coding gene on chromosome 19 (7,739,993 to 7,747,564, reverse strand). Ensembl gene ENSG00000090659.
Subcellular location: Membrane raft (Isoform 1); Cell membrane (Isoform 2); Cell membrane (Isoform 3); Cell membrane (Isoform 4); Cell membrane (Isoform 5); Secreted (Isoform 6); Secreted (Isoform 7); Secreted (Isoform 8); Secreted (Isoform 9); Secreted (Isoform 10); Secreted (Isoform 11); Secreted (Isoform 12)
Pathways (Reactome):
Disease: Dengue Virus Attachment and Entry; RSV-host interactions
Immune System: Butyrophilin (BTN) family interactions; CD209 (DC-SIGN) signaling
Gene Ontology:
Molecular function: cell adhesion receptor activity; protein binding; virus receptor activity; carbohydrate binding; D-mannose binding; pattern recognition receptor activity; peptide antigen binding; virion binding
Biological process: B cell adhesion; dendritic cell migration; immature T cell proliferation; leukocyte cell-cell adhesion; positive regulation of T cell proliferation; positive regulation of viral life cycle; regulation of T cell proliferation; symbiont entry into host cell; antigen processing and presentation; cell-cell recognition; heterophilic cell-cell adhesion; immune response; intracellular signal transduction; intracellular transport of virus; peptide antigen transport; viral genome replication; virion attachment to host cell
Cellular component: cell surface; external side of plasma membrane; membrane raft; plasma membrane; cytoplasm; endosome membrane; membrane; extracellular region; host cell
Genetic constraint (gnomAD): Loss-of-function variants: 30 observed, 43.03 expected, observed/expected ratio (o/e) 0.7, 90% interval 0.52 to 0.95. The upper end of that interval is the gene's LOEUF score, 0.95, which puts it in group 4 of 6, group 1 being the genes least tolerant of losing a copy. Missense variants: 392 observed, 449.38 expected, observed/expected ratio (o/e) 0.87, 90% interval 0.8 to 0.95. Synonymous variants: 163 observed, 177.89 expected, observed/expected ratio (o/e) 0.92, 90% interval 0.81 to 1.04.
Homologues: Orthologues: macaque CD209 (82% identical), chimpanzee CD209 (50% identical), mouse Cd209b (39% identical), rat Clec4m (38% identical), guinea pig Cd209 (35% identical), rat Cd209d (35% identical), rat Cd209a (34% identical), mouse Cd209d (34% identical), mouse Cd209a (33% identical), rat Cd209c (32% identical), mouse Cd209e (31% identical), rat Cd209e (30% identical), and 23 more. Paralogues in human: CLEC4M (71% identical), CLEC17A (17% identical), CLEC4E (17% identical), CLEC10A (16% identical), CLEC4G (16% identical), ASGR1 (16% identical), CLEC4C (16% identical), CLEC4D (15% identical), ASGR2 (15% identical), CD207 (14% identical), FCER2 (14% identical), CLEC4A (14% identical), and 2 more.
Diseases named in the same sentence as CD209 in open-access papers:
CD209 is named in the same sentence as 205 diseases in open-access papers, as found by Europe PMC text mining. Sharing a sentence is not in itself a finding about the gene and the disease. The quoted sentences say what the papers report.
viral infection (66 papers, 2005 to 2025). "Single nucleotide polymorphisms of the MBL2, FCN and CD209 genes with associations with virus infections." (PMID 25642836, 2015). "Also, the decreased expression of CD209 in DCs of COVID-19 lungs may be a result of cell death caused by direct viral infection to DC-SIGN expressed DCs." (PMID 34502134, 2021). "Using in vitro cell models, we show that the type C lectin receptor pathway member DC-SIGNR1 (CD209) is an essential factor during acute virus infection." (PMID 41150440, 2025). "It is also necessary to evaluate the effect of dimeric IgA in viral infection of CD209 knockout animals in the future." (PMID 37542391, 2023). "DC-SIGN is also referred to as CD209 and is a PRR that recognizes and binds to mannose residues, a conserved PAMP associated with a variety of viral infections." (PMID 30791481, 2019). "All in all, we established an animal component-free in vitro model to generate primary CD11c+CD209+-moDCs by use of hPL, which is a valuable tool to study viral infections and interactions in vitro and under more defined conditions compared to FCS-generated DCs." (PMID 41041316, 2025). "It has been shown previously that the CD209 is an endocytic receptor for viral infection." (PMID 39846844, 2025). "CD209+ cells were increased and permissive to viral infection in the olfactory epithelium of Syrian hamsters upon SARS-CoV-2 infection, suggesting that this cell population could contribute to viral mucosal seeding." (PMID 37542391, 2023). "Attachment of virus particles to the host cell surface is a significant rate-limiting step to virus infection in vitro, but can be overcome in part by spinoculation, the inclusion of polycations that enhance viral binding, or the expression of virus attachment factors such as CD209 or CD209R." (PMID 22693444, 2012). "Among them, blocking CD209 inhibits viral entry and CH25H can suppress viral infection by modulating innate immunity and virus-specific adaptive immunity." (PMID 38648200, 2024). "DC-SIGN (CD209) mediates pathogen endocytosis and antigen presentation, and is known to be involved in multiple viral infections, including SARS-CoV and influenza A virus." (PMID 35255492, 2022). "DC-SIGN (CD209) and its homolog L-SIGN (also called DC-SIGNR, CD209L) are one of the most investigated C-type lectins involved in viral infection." (PMID 25642837, 2015). "BAY-M2d induced multiple antiviral genes (TLR7, CD74, CES1, HLA-DOA, CD209, and CMPL2), the products of which may be involved in resistance to viral infections." (PMID 40129989, 2025). "Interestingly, we also detected high expression levels of antibacterial genes (SAA, CHTA−2B, CMPK2, CD209, LECT2, and NK−lysin) by RNA−seq, suggesting that viral infection disrupts the microbial balance of the gut." (PMID 36016461, 2022).
HIV-1 infection (42 papers, 2008 to 2025). The type species of lentivirus and the etiologic agent of acquired immunodeficiency syndrome (AIDS). "CD209 expression has been reported in association with HIV-1 infection." (PMID 21226936, 2011).
dengue (37 papers, 2008 to 2025). "The rs2287886 SNP in the CD209 promoter region has been linked to severe dengue fever and cytomegalovirus disease, predisposition to the development of tick-borne encephalitis, and invasive pulmonary infection by Aspergillosis." (PMID 41009975, 2025). "A single nucleotide polymorphism (SNP) in the promoter of CD209/DC-SIGN was associated to increased risk of developing dengue fever." (PMID 26645066, 2015). "Other dengue illness severity-related polymorphisms include DC-SIGN (CD209), transporters associated with antigen presentation (TAPs), Fc receptor, cytotoxic lymphocyte antigen 4 (CTLA4), mannose binding lectin-2 (MBL-2) and cytokine genes TNF-α, and TGF-β." (PMID 24623445, 2014). "Previous studies have reported that the CD209 promoter single nucleotide polymorphism (SNP)-336A/G exerts an effect on CD209 expression and is associated with human susceptibility to dengue, HIV-1 and tuberculosis in humans." (PMID 18167547, 2008). "Furthermore, a variant in the CD209 promoter was associated with severity of dengue disease, which supports the importance of DC-SIGN in DENV infection." (PMID 30042931, 2018). "A study of dengue fever, a common tropical disease in Thailand, showed a variant in CD209 having a crucial role in dengue pathogenesis which may allow for preventive strategies." (PMID 24936510, 2014). "For DENV infection, a variant in the promoter region of the DENV receptor DC-SIGN/CD209 and the pattern recognition receptor (PRR) Toll-like receptor 4 (TLR4) haplotypes have been found associated with severity of dengue disease." (PMID 32576686, 2020). "Even the immune system genes associated with dengue illness, such as TNF-α, IL-10, TGF-β1, FcγRIIa and CD209, can also be related with the RXRA gene in several pathways, as their expression is controlled by dimers formed by RXRA and other nuclear factors." (PMID 28241052, 2017). "Diverse single nucleotide polymorphisms (SNPs) in genes such as HLA-I, HLA-II, TNF-α, IL-10, TGF-β1, FcγRIIa, VDR, CD209 and OAS have been associated with symptomatic dengue or considered protective against the disease, in Asian and Latin American populations." (PMID 28241052, 2017). "Some studies have demonstrated that genetic variations of CD209 (rs4804803) were associated with the susceptibility to HIV, Mycobacterium tuberculosis, HCV, and dengue." (PMID 21245921, 2011). "There has been considerable recent interest in the role of CD209 variation in human susceptibility to infectious diseases including M. tuberculosis and M. leprae, HIV-1, and Dengue." (PMID 18167547, 2008). "There is evidence that infection of immature myeloid dendritic cells plays a crucial role in dengue pathogenesis and that the interaction of the viral envelope E glycoprotein with CD209/DC-SIGN is a key element for their productive infection." (PMID 18827881, 2008). "Dermal macrophages express CD209, yet little is known about their role in dengue virus infection." (PMID 18827881, 2008).
COVID-19 (32 papers, 2020 to 2025). A disease caused by infection with severe acute respiratory syndrome coronavirus 2. "Another study showed that the ABO locus mediated the risk of COVID-19 by influencing the modulation of CD209, one of the binding sites for the SARS-CoV-2 virus." (PMID 41009975, 2025). "This research explored the role of the rs2287886 polymorphism within the CD209 gene in the context of severe COVID-19." (PMID 41009975, 2025). "Our results suggest that the GG genotype of the rs2287886 CD209 polymorphism is associated with an increased risk of severe COVID-19 in the Brazilian population and serves as a potential biomarker." (PMID 41009975, 2025). "Although there are some studies on the effects of rs2287886 of the CD209 gene on some diseases, studies regarding its association with COVID-19 remain limited." (PMID 41009975, 2025). "This is in line with our findings that CD209 increased the risk of severe COVID-19, COVID-19 hospitalization and SARS-COV2 infection." (PMID 38575325, 2024). "Recent studies also showed that one of the COVID-19 risk variants, rs657152-A, was associated with increases in the CD209 antigen and facilitated the infection of SARS-CoV-2, SARS-CoV, and other viruses." (PMID 35783255, 2022). "For example, rs505922, a trans-eQTL of CD209 was found to be associated with increased CD209 levels and COVID-19 severity." (PMID 35618891, 2022). "We found CD209 expression and the percentage of DCs and MoD Mø or monocytes were associated with COVID-19 severity." (PMID 34502134, 2021). "To investigate the association of CD209 expression and DCs with COVID-19 risk, we next systematically investigated the cell type-specific expression of CD209 in upper airway, lower airway and peripheral blood." (PMID 34502134, 2021). "Using a GWAS of severe COVID-19 as the querying phenotype in iCPAGdb revealed shared SNPs associated with idiopathic pulmonary fibrosis and plasma protein levels of CD209, a possible receptor for SARS-CoV-2." (PMID 34001247, 2021). "One protein, called CD209 (also known as DC-SIGN), is involved in how the virus enters the host cells, and had one of the strongest associations with COVID-19." (PMID 34402426, 2021). "The “A” allele of rs657152 associated with increased risk of COVID-19 with respiratory failure is also associated with increased levels of CD209." (PMID 34001247, 2021). "Further investigation is required to elucidate this interaction and the causal effect of ACE2 or CD209 to the COVID-19 risk." (PMID 34502134, 2021). "Our findings suggest that the rs2287886 polymorphism in the CD209 gene may influence COVID-19 severity." (PMID 41009975, 2025). "GTEx eQTL analysis indicated higher expression of the CD209 gene in individuals with the GG genotype, suggesting that individuals carrying the G allele might have greater susceptibility to COVID-19 severity." (PMID 41009975, 2025). "Moreover, we identified several other inflammation-related proteins that are linked to COVID-19, such as CD209, CD58, CCL15, CCL28, and MNDA." (PMID 38575325, 2024). "Most interestingly, the ABO locus is associated with both COVID-19 and CD209 (p = 0.008)." (PMID 34001247, 2021). "In conclusion, we integrated genetic investigation with functional assessments of CD209, a receptor in moDCs, and postulated that this target may convey the COVID-19 risk of the ABO signal." (PMID 34402426, 2021). "Thus, iCPAGdb and subsequent colocalization analysis support a model where ABO regulates CD209 protein levels to impact COVID-19 risk, though much future experimental and clinical studies will be required to fully test this hypothesis." (PMID 34001247, 2021). "Thus, the data suggest that the interaction between CD209 and its associated proteins may play a role in modulating immune responses, particularly T-cell activation and host defense, influencing the susceptibility and severity of COVID-19." (PMID 41009975, 2025).
COVID-19 (continued). "This study explored the potential correlation of the CD209 gene SNP rs2287886 with diverse COVID-19 patient outcomes." (PMID 41009975, 2025). "CD209 was found to be decreased in lungs but increased in blood of COVID-19 DCs, with cDC2 decreased in both lung and blood in disease but increased in lungs with severity." (PMID 36851285, 2023). "First, we showed that genetically predicted circulating ABO protein was associated with COVID-19 susceptibility and severity and the lead ABO signal was associated strongly with plasma concentrations of soluble CD209." (PMID 34402426, 2021). "In DCs, we found CD209 expression was decreased in lungs but increased in blood of COVID-19 cases, as compared to healthy controls." (PMID 34502134, 2021). "Out of 22 eligible articles that investigated candidate genes (2 as associated with COVID-19), the top-ranked genes in the number of studies were ACE2, CLEC4M (L-SIGN), MBL, MxA (n = 3), ACE, CD209, FCER2, OAS-1, TLR4, TNF-α (n = 2)." (PMID 32917282, 2020). "Considering that CD209 may act as a receptor for SARS-CoV-2, these results could enhance our understanding of genetic susceptibility to severe COVID-19." (PMID 41009975, 2025). "Although we highlighted hACE2 as a binding partner of SARS-CoV-2, a number of studies presented different docking partners of the human host to SARS-CoV-2 infections, such as NRP1, L-SIGN(CLEC4M), DC-SIGN(CD209), and CD147(BSG)." (PMID 35816517, 2022). "Previous studies have shown that ACE2 is barely detected in immune cells, such as T/B cells, which suggests that lymphocytopenia in patients with COVID-19 might be explained by the high expression of CD209 in lymphoid tissue." (PMID 35783255, 2022). "Likewise, the proportion of CD209 in macrophage/monocyte cells and dendritic cells was increased in the lungs of COVID-19 patients compared to in healthy lungs." (PMID 35458567, 2022). "To validate this as a relevant target for COVID-19, we experimentally tested whether CD209 directly interacts with SARS-CoV-2, as had been recently proposed based on similarities to SARS-CoV-1, which was reported to bind CD209." (PMID 34402426, 2021). "We performed colocalization analysis of the GWAS signals for COVID-19 and CD209 protein levels." (PMID 34001247, 2021). "We demonstrated experimentally that CD209 directly interacts with the spike protein of SARS-CoV-2, suggesting a mechanism that could explain the ABO association with COVID-19." (PMID 34402426, 2021). "Further investigation of cross-phenotype SNPs associated with both severe COVID-19 and other human traits demonstrated colocalization of the GWAS signal at the ABO locus with plasma protein levels of a reported receptor of SARS-CoV-2, CD209 (DC-SIGN)." (PMID 34001247, 2021). "Materials and Methods: Clinical exome data of 103 individuals was analyzed to identify sequence variants in five selected candidate genes: ACE2, TMPRSS2, CD209, IFITM3, and MUC5B to assess their prevalence and role to understand the COVID-19 infectivity and progression in our population." (PMID 33101356, 2020). "High CD209 expression in the small intestine and adipose tissue, as shown by GTEx analysis, indicates potential primary sites for SARS-CoV-2 infection, and increased expression in lymphoid tissues may underlie lymphocytopenia in COVID-19 patients." (PMID 41009975, 2025). "Moreover, the elevated level of CD209 may be a possible reason for more severe clinical symptoms in COVID-19-infected obese patients." (PMID 35783255, 2022). "Indeed, we found higher gene expression of ACE2 and CD209 in upper airway cells of COVID-19 ARIs compared to non-viral ARIs, and CD209 plasma protein expression was correlated COVID-19 risk and severity." (PMID 34502134, 2021). "Compared to the healthy donors, the proportion of macrophage/monocyte cells expressing CD209-CTSL and FURIN was increased, whereas the proportion of dendritic cells expressing CD209-CTSL was unchanged in COVID-19 patients’ lungs." (PMID 35458567, 2022).